RNU1-77P (RNA, U1 small nuclear 77, pseudogene)
Gene: Small nuclear RNA gene on chromosome 15 (82,174,224 to 82,174,385, reverse strand). Ensembl gene ENSG00000212170.
Homologues: Orthologues: chimpanzee U1 (98% identical), guinea pig U1 (70% identical), dog U1 (69% identical). Paralogues in human: RNU1-1 (87% identical), RNU1-2 (87% identical), RNU1-27P (87% identical), RNU1-28P (87% identical), RNU1-3 (87% identical), RNU1-4 (87% identical), RNU1-89P (87% identical), RNVU1-18 (87% identical), RNVU1-29 (87% identical), U1 (87% identical), RNVU1-28 (86% identical), RNVU1-7 (86% identical), and 134 more.